RPS15A (ribosomal protein S15a)
Diseases named in the same sentence as RPS15A in open-access papers (continued):
Sharing a sentence is not in itself a finding about the gene and the disease.
osteosarcoma (3 papers, 2021 to 2025). A usually aggressive malignant bone-forming mesenchymal neoplasm, predominantly affecting adolescents and young adults. "Subsequent the loss/gain of function experiments showed that knockdown of RPS15A alleviated the promotion effects of TMED3 overexpression in osteosarcoma cells, especially in proliferation, colony formation, apoptosis and migration." (PMID 34838013, 2021). "Further research revealed that the inhibitory effect on osteosarcoma cells was enhanced by simultaneous knockdown of RPS15A and TMED3." (PMID 37928880, 2023). "TMED3 was identified as a potential target of Ribosomal protein S15A (RPS15A) among the regulated downstream genes in osteosarcoma." (PMID 34838013, 2021). "Through IHC analysis, we found that the expression of RPS15A in tumor tissues of osteosarcoma was significantly higher than that of normal tissues adjacent to the cancer." (PMID 34838013, 2021). "On the other hand, the mRNA expression levels of RPS15A in human osteosarcoma cells (U-2OS, Saos-2, MNNG/HOS, MG-63) was higher than the osteoblast cells hFOB 1.19." (PMID 34838013, 2021). "More importantly, knockdown of RPS15A alleviated the promotion effects of TMED3 overexpression in osteosarcoma cells." (PMID 34838013, 2021). "The loss-of-function assays explained that the inhibitory effects of RPS15A knockdown on the progression of osteosarcoma cells was similar to that of TMED3." (PMID 34838013, 2021). "Compared with other groups, knockdown of RPS15A inhibited the viability of osteosarcoma cells most significantly." (PMID 34838013, 2021). "Of note, the analysis results of the TARGET-OS database showed that RPS15A was abundantly expressed in osteosarcoma." (PMID 34838013, 2021). "Notably, the pro-moter impact of TMED3 overexpression in osteosarcoma cells was reduced by downregulating RPS15A." (PMID 37928880, 2023). "Furthermore, protein S15A (RPS15A) was discovered to be a downstream target of TMED3 that contributes to the development of osteosarcoma." (PMID 37928880, 2023). "Importantly, knockdown of RPS15A alleviated the promotion effects of TMED3 overexpression in osteosarcoma cells." (PMID 34838013, 2021). "Consistently, the present study determined the abundant expression of RPS15A in osteosarcoma." (PMID 34838013, 2021). "Furthermore, knockdown of RPS15A alleviated the promotion effects of TMED3 overexpression in osteosarcoma cells." (PMID 34838013, 2021). "Collectively, our study indicated that TMED3/RPS15A axis played vital roles in osteosarcoma progression and which might become a potential therapeutic target for osteosarcoma treatment." (PMID 34838013, 2021). "In summary, these findings emphasized the importance of TMED3/RPS15A axis in promoting tumor progression, which may be a promising candidate for molecular therapy of osteosarcoma." (PMID 34838013, 2021). "Additionally, ribosomal protein S15A (RPS15A) was determined as a potential downstream target for TMED3 involved in the progression of osteosarcoma." (PMID 34838013, 2021). "Further investigation was required to determine whether RPS15A could regulate osteosarcoma progression." (PMID 34838013, 2021). "Additionally, research has shown that knocking down the ribosomal protein S15A (RPS15A) using a lentiviral-mediated RNA interference system can significantly inhibit the proliferation and colony formation of human osteosarcoma U2OS cells, causing them to arrest in the G0/G1 phase of the cell cycle." (PMID 40831924, 2025). "Therefore, TMED3/RPS15A axis may play a role in promoting the development and progression of osteosarcoma, which may provide a blueprint for the therapeutic target of osteosarcoma." (PMID 34838013, 2021). "Therefore, we suspected that TMED3 may modulate the apoptotic signaling via targeting RPS15A and regulating its activity in osteosarcoma, which certainly still warrants our further investigation." (PMID 34838013, 2021).
osteosarcoma (continued). "Analogously, in order to determine the effects of RPS15A and TMED3 on osteosarcoma, experimental groups of TMED3 + NC-shRPS15A, shRPS15A + NC-TMED3, TMED3 + shRPS15A and shRPS15A + shTMED3 were established in MNNG/HOS cells." (PMID 34838013, 2021). "Further investigations elucidated that the simultaneous knockdown of RPS15A and TMED3 intensified the inhibitory effects on osteosarcoma cells." (PMID 34838013, 2021). "According to the TARGET-OS database, the expression of RPS15A and TMED3 in osteosarcoma was significantly positively correlated through Spearman analysis." (PMID 34838013, 2021). "The simultaneous knockdown of RPS15A and TMED3 intensified the inhibitory effects on osteosarcoma cells in terms of proliferation, apoptosis and migration." (PMID 34838013, 2021). "Accordingly, the relationship between RPS15A and TMED3 in osteosarcoma aroused our interest." (PMID 34838013, 2021).
colon cancer (2 papers, 2021 to 2022). "In colon cancer, the highest correlation was found between CD4+ T cells and RPS14 (correlation = −0.5) and CD4+ T and RPS15A (correlation = −0.49), as well as dendritic cells and RPS3 (correlation = −0.49)." (PMID 35127345, 2022). "Similarly, the knockdown of RPS9, RPS15a and RPS27 inhibit human colon cancer cell growth and proliferation." (PMID 34873618, 2021).
glioma (2 papers, 2016 to 2021). A benign or malignant brain and spinal cord tumor that arises from glial cells (astrocytes, oligodendrocytes, ependymal cells). "In this study, we firstly evaluated the relative expression of RPS15A in glioma tissues and normal tissues and found it was significantly up-regulated in GBM tissues compared with that in normal tissues." (PMID 27130037, 2016). "We firstly found the messenger RNA (mRNA) levels of RPS15A were significantly up-regulated in glioma compared that in normal tissues using the datasets from Oncomine database." (PMID 27130037, 2016). "Down-regulation of RPS15A could induce apoptosis of glioma cells." (PMID 34307151, 2021).
ovarian carcinoma (2 papers, 2021 to 2025). A malignant neoplasm originating from the surface ovarian epithelium. "RPS15AP12 enhances the growth ability and metastatic capabilities of ovarian cancer (OC) cells via functioning as a competitive endogenous RNA (ceRNA) for its host gene, RPS15A, through the sequestration of miR‐96‐3p." (PMID 40000433, 2025). "The RPS15AP12/ RPS15A axis exhibits an anti‐tumour effect via inhibiting innate immune response in ovarian cancer." (PMID 40000433, 2025).
Sepsis (2 papers, 2025 to 2026). Sepsis is defined as life-threatening organ dysfunction caused by a dysregulated host response to infection. "Clinical qPCR validation confirmed that RPLP0 was significantly upregulated in sepsis patients, while CD52, RPS15A, and RPS18 were downregulated." (PMID 42291321, 2026).
esophageal adenocarcinoma (1 paper, 2021). A malignant tumor with glandular differentiation arising predominantly from Barrett mucosa in the lower third of the esophagus. "The expression levels of CSE1L, RPS15A, SFPQ, and CAPZB in ESCC were significcantly higher than those in normal tissue and esophageal adenocarcinoma (EAC)." (PMID 33842377, 2021).
hypoplastic left heart syndrome (1 paper, 2025). Hypoplastic left heart syndrome (HLHS) refers to the abnormal development of the left-sided cardiac structures, resulting in obstruction to blood flow from the left ventricular outflow tract. "Characterization of RPS15A from the 75H hypoplastic left heart syndrome (HLHS) index family." (PMID 41379537, 2025).
ischemic stroke (1 paper, 2022). A stroke disorder caused by obstruction of blood flow to the brain, due to thrombotic (local blood clot formation) or embolic (due to a blood clot or other material traveling from another site) event. "However, the dysfunction of RPS15A, RPS6, and RPS28 in females with ischemic stroke patients has never been reported." (PMID 35432523, 2022).
lymphoma (1 paper, 2022). A malignant (clonal) proliferation of B- lymphocytes or T- lymphocytes which involves the lymph nodes, bone marrow and/or extranodal sites. "Besides lymphoma, raised free levels of several RPs (RPS15A, RPL23A, RPS26 and RPS29) have been associated with aggressiveness and bad prognosis also in other malignancies." (PMID 36226068, 2022).
cancer (19 papers, 2016 to 2025). A tumor composed of atypical neoplastic, often pleomorphic cells that invade other tissues. "RPS15A has also been implicated in other cancers, including liver cancer, osteosarcoma, and lung cancer, highlighting its potential as an antitumor target." (PMID 40943089, 2025). "While an increase in RPS15A associates with the progression of various cancers, a decrease in RPS15A inhibits cancer cell proliferation." (PMID 39086661, 2024). "Among these genes, RPS15A (Ribosomal protein s15a) was shown to be related to many cancers in previous studies." (PMID 37508365, 2023). "Increasing evidence suggests that RPS15A exerts critical functions in the development and progression of cancer." (PMID 35432523, 2022). "As the components of ribosome, Rps15a, Rps19, Rpl14, Rpl22 were preciously controlled by Myc and highly expressed in cancer cells, which promoted the EMT process." (PMID 34955855, 2021). "In addition, KEGG pathway enrichment analysis indicates that MCM8/RPS15A axis also plays an important role in cell senescence and MicroRNA in cancer." (PMID 38988047, 2024). "Examples of RPLs and RPSs include RPL15, RPL19, RPS6 and RPS15A, which have been associated with a negative prognosis in malignant neoplasms of the digestive system." (PMID 38804617, 2024). "Given that epithelial‐mesenchymal transition (EMT) is considered a striking feature of most cancers and plays a crucial role in cancer metastasis and invasion, we then examined whether EMT might be an underlying mechanism for RPS15A‐induced GC metastasis." (PMID 30661291, 2019). "Similar effects of RPS15A were demonstrated in previous studies in other cancer types." (PMID 27130037, 2016). "Our results showed that the knockdown of RPS15A could inhibit cancer cell growth and colony formation in vitro, as well as induced cell cycle arrest at G0/G1 phase and cell apoptosis." (PMID 27130037, 2016). "Furthermore, flow cytometry analysis data showed that RPS15A silencing induced apoptosis as characterized by the prominent presence of apoptotic cancer cells." (PMID 26989627, 2016). "Recently, aberrantly expressed RPS15A was found in the hepatitis virus and in malignant tumors." (PMID 26989627, 2016). "Furthermore, the impacts of RPS15A silencing on the growth of the cancer cells were examined by MTT assay and colony formation assay." (PMID 26989627, 2016). "RPS15A expression levels were quite obvious in the cancer cell lines." (PMID 26989627, 2016). "In OC, transcriptional expression of RPS15A is inhibited by FOXN3, which suppresses cancer progression." (PMID 40000433, 2025). "Recently, it was demonstrated that RPS15A (ribosomal protein S15A) expression is increased in lung ADC tissue and knockdown of RPS15A inhibited cancer cell growth and induced apoptosis." (PMID 32536039, 2020). "RPS15A, although not extensively studied, has emerged as a significant marker in cancer biology." (PMID 40943089, 2025). "Furthermore, we observed that both the mRNA and protein levels of a collection of NF‐κB downstream effectors that are central co‐ordinators of cancer cell metastasis, such as ICAM1, VCAM1 and MMP9, were decreased by RPS15A knockdown, but increased by RPS15A overexpression." (PMID 30661291, 2019).
tumor (16 papers, 2016 to 2025). "Indeed, the overexpression of RPS15A in HCC is linked to an increase in fibroblast growth factor 18 (FGF18) expression following the stimulation of Wnt/β-catenin pathway which induces tumor angiogenesis." (PMID 34873618, 2021). "RPS15AP12‐lncRNA, regulated by m6A, competes with RPS15A for miR‐96‐3p binding, thereby inhibiting innate immune pathways and facilitating tumour progression." (PMID 40000433, 2025). "On the contrary, overexpression of RPS15A enhanced the ability of subcutaneous tumour formation and intraperitoneal metastasis of OC cells in xenografts." (PMID 40000433, 2025). "In breast tumor tissues, a higher expression of RPS15A is detected and correlates with larger tumor size and higher TNM stage." (PMID 34873618, 2021). "RPS15A is overexpressed in renal cell carcinoma and related to tumor growth as its inhibition promotes apoptosis." (PMID 34873618, 2021). "The tumours from RPS15A‐overexpressed MGC‐803 cells showed more active proliferative ability than the control group (n = 5 for each group)." (PMID 30661291, 2019). "The promotive role of RPS15A in tumour progression has been increasingly recognized recent years, whereas the underlying molecular mechanism remains largely unclear." (PMID 30661291, 2019). "RPS15A over-expression also facilitates hepatocellular growth via promoting cell cycle transition and accelerates tumor formation in vitro, whereas RPS15A mRNA down-regulation inhibited hepatic cancer cell growth." (PMID 26989627, 2016). "Knockdown of RPS15A could also impair the ability of subcutaneous tumour formation and intraperitoneal metastasis of OC cells in xenografts." (PMID 40000433, 2025). "Importantly, the deletion of RPS15AP12 diminishes the expression of RPS15A, leading to the upregulation of anti‐tumour immune responses by activating RIG‐I and MDA5 and downstream p‐TBK1 and p‐IRF3 as well as IFN‐β levels." (PMID 40000433, 2025). "By utilizing integrative RNA‐seq, we found that blocking the RPS15AP12/miR‐96‐3p/RPS15A axis had an anti‐tumour effect via innate immune responses, as it decreased OC cell proliferation, increased the expression of RNA sensors RIG‐I and MDA‐5, and activated the downstream type I IFN pathway." (PMID 40000433, 2025). "Moreover, MCM8 knockdown inhibited tumor growth, RPS15A expression, and phosphorylation of P38α, LYN, and p70S6K in vivo." (PMID 38988047, 2024). "The finding that RPS15A knockdown inhibits angiogenesis and tumor growth is also in line with our hypotheses that the overexpression of ribosomal proteins causes OIS disruption and tumor progression." (PMID 38388496, 2024). "RPS15A located on human chromosome 16p12.3 promoted the binding of mRNA and ribosome in the early stage of translation progression, and the abnormal expression of RPS15A played a crucial role in development and progression of tumor." (PMID 35256584, 2022). "In conclusion, RPS15A expression was increased in tumor tissues." (PMID 26989627, 2016). "Thus our data would be helpful to augment the tumour biology of RPS15A." (PMID 30661291, 2019). "The expression of RPS15A was significantly up‐regulated in GC samples compared to MNGM, and its expression was closely related to TNM stage, tumour size, differentiation, lymph node metastasis and poor patient survival." (PMID 30661291, 2019). "Additionally, when miR-519d-3p is overexpressed, it is considered another tumor suppressor for PDAC by regulating Wnt signaling pathway, through targeting ribosomal protein S15A (RPS15A)." (PMID 36292753, 2022).
tumor (continued). "We then analysed the relationship between RPS15A expression and clinicopathological characteristics in GC patients, and found that RPS15A expression was closely correlated with aggressive phenotypes of GC, including TNM stage, tumour size, differentiation and lymph node metastasis." (PMID 30661291, 2019). "In HCC cells, several studies showed that the miR-29-3p-family acted as tumor-suppressive miRNAs via negative control of several oncogenic targets, e.g., IGF2BP1, RPS15A and LOXL2." (PMID 34199886, 2021).
infection (6 papers, 2019 to 2025). The state of being infected such as from the introduction of a foreign agent such as serum, vaccine, antigenic substance or organism. "MT4A and RPS15A were differentially upregulated in root cap cells after Foc TR4 infection compared with the control." (PMID 41220693, 2025). "There were 10 common downregulated transcripts with a further six being unique to the synchronised infection (i.e., Hist4h4, 2900010M23Rik, Churc1, Rps15a, Lgals1, S100a16)." (PMID 31546628, 2019).
digestive system tumors (1 paper, 2024). "Previous studies have reported that RPS15A is a carcinogenic among digestive system tumors." (PMID 38988047, 2024).
metabolic disorders (1 paper, 2020). "Mutations in one other gene (RPS15A) generally result in metabolic disorders." (PMID 32004313, 2020).
neurological disorders (1 paper, 2006). "Our analysis revealed that the human RPS4X, RPS15A, and RPLP0 genes are located in chromosomal regions linked to brain or neurological disorders, and brain regions were affected in the morphants for these genes." (PMID 17183665, 2006).
RPS15A also shares sentences with these, for which no sentence is quoted: prostate carcinoma (3 papers); acute myeloid leukemia (2); colorectal cancer (2); nasopharyngeal carcinoma (2); non-small cell lung carcinoma (2); anaplastic oligoastrocytoma (1); brain cancer (1); diffuse astrocytoma (1); esophageal cancer (1); HCMV infection (1); lymph node metastasis (1); myelodysplastic syndrome (1); oligodendroglioma (1); papillary thyroid cancer (1); psoriasis (1); Stroke (1); T-cell acute lymphoblastic leukemia (1); tauopathies (1).